CASP1 (caspase 1)
Diseases named in the same sentence as CASP1 in open-access papers (continued):
Sharing a sentence is not in itself a finding about the gene and the disease.
oropharyngeal cancer (1 paper, 2025). Carcinoma, predominantly squamous cell, arising from the epithelial cells of the oropharynx. "In relation to oral and oropharyngeal cancer, significant associations were observed for a suite of genes including HSPA5, TNFAIP6, AKR1C1, CASP1, ANXA1, and MYC." (PMID 41023518, 2025).
otitis media with effusion (1 paper, 2021). Otitis media associated with accumulation of fluid in the middle ear. "Spearman correlation analysis between levels of caspase-1, IL-1β, and IL-18 in the middle ear effusion and the duration of otitis media with effusion." (PMID 34805037, 2021).
Ovarian Failure (1 paper, 2021). "Therefore, we hold the opinion that Mox inhibits TXNIP/NLRP3/caspase-1 signaling-medicated pyroptosis and alleviates ovarian failure in POF." (PMID 33613687, 2021).
pemphigus (1 paper, 2025). Pemphigus is a group of rare autoimmune diseases that cause blistering of the skin and mucous membranes (mouth, nose, throat, eyes, and genitals).This conditioncan occur at any age, but often strikes people in middle or older age. "The effect of pyroptosis-specific Caspase-1 inhibitors supports the idea of pyroptosis in pemphigus pathogenesis and highlights the potential for targeting specific Caspases in pemphigus treatment." (PMID 40102153, 2025). "Exploring the role of pyroptosis in pemphigus pathogenesis and its therapeutic implications requires digging deeper into Caspase activation and how Caspase inhibitors, particularly those targeting Caspase-1, can help treat the disease." (PMID 40102153, 2025).
Peri-Implantitis (1 paper, 2025). An inflammatory process with loss of supporting bone in the tissues surrounding functioning DENTAL IMPLANTS. "A cross-sectional study showed that inflammasomes (AIM2, NLRP3), and their downstream effectors (interleukin-1β, caspase-1), are strongly associated with specific bacteria in peri-implantitis." (PMID 40851867, 2025).
periodic fever syndrome (1 paper, 2023). Fevers of unknown etiology recurring over months or years. "Caspase-1 mutations may lead to inefficient auto-processing and reduced catalytic activity, abolishing downstream signaling, disrupting the equilibrium of caspase-1-centered inflammatory regulation, and resulting in numerous inflammatory disorders (e.g., periodic fever syndromes)." (PMID 37090724, 2023).
peripheral nerve injury (1 paper, 2010). Injury to a peripheral nerve. "Contrary to these results, it was shown that although spinal glial-derived IL-1β is fundamental for the development of neuropathic pain after peripheral nerve injury, caspase-1 is not involved in this process." (PMID 20920345, 2010).
pneumococcal pneumonia (1 paper, 2021). A febrile disease caused by STREPTOCOCCUS PNEUMONIAE. "Here, we show that bacterial lysates exert protection against pneumococcal pneumonia independently of neutrophils, IL-17A or Caspase-1/11 activation, suggesting the existence of redundant mechanisms of protection." (PMID 33981296, 2021).
polycystic kidney disease (1 paper, 2022). A usually autosomal dominant and less frequently autosomal recessive genetic disorder characterized by the presence of numerous cysts in the kidneys leading to end-stage renal failure. "Is Caspase-1/inflammasome activation a common feature of all renal injuries that promote polycystic kidney disease?" (PMID 36523654, 2022). "Caspase-1 knockout in female but not male RC mice restrains MYC and YAP pathways, which are central mediators of kidney pathogenesis in polycystic kidney disease." (PMID 36523654, 2022).
prediabetes (1 paper, 2025). "A significant overactivation of the inflammasome was observed in the prediabetes control group compared to healthy control subjects, as indicated by the results obtained through NLRP3, caspase-1, and IL-1β protein concentrations." (PMID 40761804, 2025).
primary effusion lymphoma (1 paper, 2024). A large B-cell lymphoma located in the body cavities, characterized by pleural, peritoneal, and pericardial fluid lymphomatous effusions and that is always associated with human herpes virus-8 (HHV-8). "Primary effusion lymphoma (PEL) cells show evidence of NRLP3 inflammasome activation, such as the presence of active caspase-1 and cleavage of pro-IL-1β and pro-IL-18." (PMID 38397043, 2024).
ptosis (1 paper, 2020). The drooping of the upper eyelid. "AIM2 and NLRP3 act as sensors to take part in the activation of caspase-1, which catalyzes neuroinflammation and ptosis." (PMID 32377306, 2020).
reflux esophagitis (1 paper, 2025). "Our study found that miR- 223 - 3p is significantly downregulated in the reflux esophagitis model, whereas NLRP3 and its downstream effectors, such as caspase- 1, IL- 1β, and IL- 18, are significantly upregulated." (PMID 40360974, 2025). "The results revealed a significant decrease in miR- 223 - 3p expression during the development of reflux esophagitis in HET- 1 A cells (P < 0.001), accompanied by significant increases in the expression levels of caspase- 1, NLRP3, and GSDMD (P < 0.05)." (PMID 40360974, 2025).
Respiratory tract infection (1 paper, 2013). An infection of the upper or lower respiratory tract. "Our findings concerning caspase-1 dependent IL-1β release suggest a role for the inflammasome in respiratory tract infections with NTHi which may be relevant for the pathogenesis of bacterial exacerbations in COPD." (PMID 23840534, 2013).
reticulum cell sarcoma (1 paper, 2023). An antiquated term that refers to a non-Hodgkin lymphoma composed of diffuse infiltrates of large, often anaplastic lymphocytes. "Compounds 154, 155, 157 and 158 from Callicarpa arborea showed potent inhibitory effects against the NLRP3 inflammasome by inhibiting Casp-1 activation and IL-1β in reticulum cell sarcoma cells." (PMID 37375299, 2023).
retinal detachment (1 paper, 2019). An eye emergency condition which may lead to blindness if left untreated. "In support of this, a study involving a mouse retinal detachment model showed that photoreceptor cell death was reduced when IL-1β and CASP1 were inhibited, as well as in Nlrp3−/− mice with retinal detachment, also indicating a role for inflammasome activation in this disease." (PMID 31379825, 2019).
rheumatic diseases (1 paper, 2024). "However, the use of caspase-1 as a serum biomarker for autoinflammatory disorders remains unknown, and the role of caspase-1 in rheumatic diseases is still unclear." (PMID 39074125, 2024).
Right ventricular hypertrophy (1 paper, 2025). In this case the right ventricle is more muscular than normal, causing a characteristic boot-shaped (coeur-en-sabot) appearance as seen on anterior- posterior chest x-rays. "Additionally, whereas hyperoxia-exposed placebo-treated animals had increased right ventricular hypertrophy, administration of caspase-1 inhibitor reduced right ventricular hypertrophy." (PMID 41231039, 2025). "Additionally, in the lung, caspase-1 inhibition improved neonatal hyperoxia-induced alveolar simplification, pulmonary vascular rarefaction and remodeling, and right ventricular hypertrophy." (PMID 41231039, 2025).
schistosomiasis (1 paper, 2019). An infectious disease caused by parasitic trematodes of the genus Schistosoma that colonize human blood vessels and release eggs that can cause granulomatous reactions leading to acute (swimmer's itch or acute schistosomiasis syndrome) or chronic disease. "The present study results showed that SEA could induce the pyroptotic death of HSCs, which was associated with the activation of caspase-1 mediated by ROS in schistosomiasis." (PMID 31610797, 2019).
scleroderma (1 paper, 2022). Scleroderma is a rare autoimmune connective tissue disorder characterized by abnormal hardening of the skin and, sometimes, other organs. "Interestingly, we found that the expression of GSDMD, caspase-1, IL-1β, and IL-18 increased significantly at the early stage (days 7 and 14) of the disease in scleroderma mice." (PMID 35396386, 2022). "Moreover, the protein levels of cleaved-GSDMD, cleaved caspase-1 and mature IL-1β were also elevated in scleroderma mice." (PMID 35396386, 2022).
spotted fever (1 paper, 2025). A type of tick-borne disease which presents on the skin caused by bacteria of the genus Rickettsia. "The “Israeli spotted fever” strain of R. conorii induces increased endothelial permeability only at the late stage of infection as evidenced by diminished electrical resistance across the endothelial monolayer, which is accompanied by caspase-1-associated pyroptotic cell death." (PMID 39679710, 2025).
status epilepticus (1 paper, 2022). Status epilepticus is defined as a continuous seizure lasting more than 30 min, or two or more seizures without full recovery of consciousness between any of them. "A study proved that the TRPV4 specific inhibitor HC067047 could block the increases in NLRP3 and caspase-1 following pilocarpine-induced status epilepticus in mice, and the experimental results are consistent with our data." (PMID 35093118, 2022).
syphilis (1 paper, 2022). A contagious bacterial infection caused by the spirochete Treponema pallidum. "A recent report described the potential role of syphilis in inducing apoptosis and pyrotosis in CD4 + and CD8 + T-lymphocytes by altering the intracellular expression of caspase-1 and caspase-3 and their levels in the circulation." (PMID 36587188, 2022).
Thrombus (1 paper, 2016). "Although the levels of pro-caspase-1 between AF(-)Thrombus(-) and AF(+)Thrombus(-) group were similar, expression of pro-caspase-1 were significantly elevated in patient with thrombus." (PMID 26930272, 2016). "The levels of cleaved caspase-1, IL-1β and cleaved IL-1β in AF(+)Thrombus(+) patients were significantly higher than those with sinus rhythm, and were elevated when compared with AF(+)Thrombus(-) patients." (PMID 26930272, 2016).
tibia fracture (1 paper, 2010). Traumatic or pathological injury to the tibia in which the continuity of the bone is broken. "Nonetheless, the involvement of caspase-1 in complex regional pain syndrome triggered by tibia fracture seems to be dependent on IL-18 processing." (PMID 20920345, 2010).
vaginal infection (1 paper, 2017). "In mouse models, experimental vaginal infection by C. albicans results in a strong inflammatory response with a marked leukocyte infiltrate essentially consisting of polymorphonuclear cells (neutrophils) and activation of caspase-1/inflammasome components." (PMID 29259175, 2017).
vitiligo (1 paper, 2022). Generalized well circumscribed patches of leukoderma that are generally distributed over symmetric body locations and is due to autoimmune destruction of melanocytes. "Further analysis of melanocytes revealed strong pyroptosis responses existed in patients with vitiligo.Results demonstrated that CASP1, CASP4, CASP6, CASP8, and GSDMD expression was significantly upregulated in melanocytes of patients with vitiligo." (PMID 35962439, 2022).
vulvovaginal candidiasis (1 paper, 2018). Infection of the vulva and vagina with a fungus of the genus CANDIDA. "Gene expression of NLRP3 inflammasome components, in particular caspase 1, by the vaginal EC has been recently reported to be the distinctive hallmark of human vulvovaginal candidiasis, substantiating previous, suggestive genetic or experimental evidence (32, –, 36)." (PMID 29789368, 2018).
infection (753 papers, 2007 to 2025). The state of being infected such as from the introduction of a foreign agent such as serum, vaccine, antigenic substance or organism. "Unlike broad-spectrum anti-inflammatory agents such as glucocorticoids, VX-765 selectively targets caspase-1, potentially reducing immunosuppressive side effects (e.g., infection risk)." (PMID 40486518, 2025). "Some reports have described that infection-induced AM disappearance is associated with caspase-1-dependent pyroptosis and TNFα-dependent apoptosis." (PMID 40060898, 2025). "The protein expression of three proteins (IL-17C, IL-18, and IL-10RB) was significantly decreased in caspase-1-deficient cells compared to Cas9 cells following HK1651 infection." (PMID 40137780, 2025). "Caspase-1- and caspase-4-deficient cells showed significantly altered cytokine and chemokine profiles after infection with A. actinomycetemcomitans, showing reduced IL-17C and IL-18 release." (PMID 40137780, 2025). "The protein expression of two proteins (CCL4 and CCL25) significantly decreased in caspase-1-deficient cells compared to Cas9 cells following HK1651 infection." (PMID 40137780, 2025). "Infection with Salmonella typhimurium induced loss of cytoskeletal marker γ-tubulin, which was prevented in caspase-1 knock out cells." (PMID 39117604, 2024). "Our findings indicate that the LM-OVA vaccine is safe in all deficient genetic backgrounds and that the caspase 1/11-GSDMD axis participates in the clearance of LM-OVA infection." (PMID 39452700, 2024). "The absence of ICP27 in the HSV-1ΔICP27-deleted viral vector caused a large rise in pro-caspase-1 RNA starting eight hours after infection, according to the real-time PCR results." (PMID 38731826, 2024). "Then, we performed peritoneal lavage at eight days post-infection (8 dpi) and found that the parasite burden was 3.6-fold greater in Casp1 deficient mice compared to WT controls." (PMID 39446964, 2024). "CS activates caspase-1 in human macrophages, which leads to macrophage dysfunction and increases the risk of infection." (PMID 39335573, 2024). "Surprisingly, Casp1 and Casp1/11 KO mice had similar long-term survival post-infection and Casp1 KO mice were protected from infection induced weight loss compared to WT mice at 35 days post infection, but consistently had higher parasite burdens." (PMID 39446964, 2024). "We discovered that caspase-1 or caspase-11 single-deficiency conferred a protective effect against infection by promoting protective inflammation." (PMID 39533032, 2024). "They detected increased susceptibility of Aim2-/- mice to intratracheal infection, which they related to decreased caspase-1 cleavage as well as lower IL-1β and IL-18 levels in the lungs." (PMID 39324136, 2024). "A deficiency of caspase-1/11 or MLKL led to a slight delay in cell death at the early stage of infection, but they were largely dispensable at later stages." (PMID 36852999, 2023). "We found that Casp1/11+/–Casp8–/–Ripk3–/– mice largely phenocopied WT B6 mice, and were resistant to infection, exhibiting minimal weight loss, diarrhea, cecal or colonic shrinkage, and no fecal blood." (PMID 36645406, 2023). "Strikingly, C. rodentium-infected Casp8–/–Ripk3–/–Casp1/11–/– mice showed severe body weight loss and died within 12 dpi, while the other cohorts survived the infection." (PMID 37080966, 2023). "Δ6 Yptb infection of two independent clones of CASP1−/− Caco-2 cells resulted in a partial loss of IL-18 release compared to WT Caco-2 cells." (PMID 37615436, 2023). "We now show that infection of caspase-1 or gasdermin D deficient macrophages by this flagellin-engineered S. Typhimurium induces apoptosis in vitro." (PMID 38055781, 2023). "We do observe that Casp1/11–/–Casp8+/–Ripk3–/– are modestly susceptible to infection while Casp1/11+/–Casp8–/–Ripk3–/– mice are fully resistant." (PMID 36645406, 2023).
infection (continued). "Infection of NLRP3- or NLRC4-deficient bone marrow-derived macrophages (BMDMs) with Salmonella revealed that inhibition of Caspase-1 by GalE was dependent on the NLRP3 inflammasome." (PMID 35630356, 2022). "Both wild-type and Casp-1,11-deficent mice on the B6 background displayed similar susceptibility with the majority of Casp-1,11-deficent mice succumbing to infection 1 day earlier than their wild-type counterparts." (PMID 34864057, 2022). "It has been shown that the NLRP3-associated protein, caspase-1, is activated upon cellular infection or stress and leads to a form of programmed cell death called pyroptosis." (PMID 35115927, 2021). "IRGB10-deficient mice, which are defective in caspase-1 activation and IL-1β release, were also shown to be susceptible to infection." (PMID 33735255, 2021). "In preterm labor, the concentration of caspase-1 in the AF is higher if labor is associated with infection and/or IAI when compared with a situation of preterm labor without infection and/or inflammation." (PMID 34572309, 2021). "Casp8/Ripk3/Casp1/11−/− mice were significantly more susceptible to lethal infection with WT B. thailandensis than were WT mice." (PMID 34154417, 2021). "The failure of Casp8/Ripk3/Casp1/11−/− BMDMs to restrict B. thailandensis intercellular spread via cell-cell fusion and intracellular replication suggested that Casp8/Ripk3/Casp1/11−/− mice would be highly susceptible to severe lethal infection." (PMID 34154417, 2021). "Pyroptosis is an inflammatory form of cell death that occurs in response to pathogenic infection and is typically driven by caspase-1 (CASP1) and/or caspase-11 (CASP11)-mediated cleavage of gasdermin D (GSDMD), which drives death by generating membrane pores." (PMID 33397971, 2021). "We next examined the impact of caspase-1 loss on the inflammatory milieu in the brain and galea during craniotomy infection." (PMID 32290861, 2020). "In agreement, we observed that Casp-1/11 deficiency also facilitates LM-OVA infection at both early (day 3) and late (day 7) stages of infection." (PMID 32328060, 2020). "We found that Casp-1/11−/− mice presented a pronounced decrease in ROS production during the acute infection and, in association, it was detected a six-fold increase of parasite burden in the genetically deficient mice." (PMID 32523898, 2020). "The Casp1−/− and Casp1/11−/− mice proved highly susceptible to infection, carrying heavy cecal, colonic and luminal pathogen burdens at 18 h p.i.." (PMID 32282854, 2020). "Inhibition of NLRP3 or caspase-1 during infection of macrophages with the severe TB causing isolate (6C4) also decreased IL-1β secretion." (PMID 32327653, 2020). "Three (3/10) Gsdmd−/− mice and one (1/10) Caspase-1-deficient mouse died within 24 h post infection, and the deaths all decreased significantly compared to those of WT mice (8/10 died)." (PMID 32922370, 2020). "NLRP3-deficient and ASC-deficient cell infection resulted in drastic loss of lytic cell death, consistent with their central role in the inflammasome and caspase-1 activation." (PMID 32854254, 2020). "Genetically deficient cells failed (partially or completely) to induce CASP-1/11 and the consequent release of the cleaved cytokines into the supernatant in response to the infection by NcLiv tachyzoites." (PMID 32523898, 2020). "Our results demonstrate that RIPK3 and Casp-1/11 deficiencies directly impact the clearance of LM-OVA infection." (PMID 32328060, 2020). "Inflammasomes, the innate immune system complexes that regulate activation of caspase-1 and IL-1 to induce inflammation in response to infection and host damage molecules (DAMPs), have been implicated in a variety of inflammatory processes including ICH." (PMID 30836997, 2019). "A wide variety of biologic effects associated with infection and inflammation are caused by the assembly of inflammasome complex, which activates caspase-1, and causes the secretion and maturation of proinflammatory cytokines IL-1β and IL-1." (PMID 31390729, 2019).